ATOX1 (antioxidant 1 copper chaperone)
Diseases named in the same sentence as ATOX1 in open-access papers (continued):
Sharing a sentence is not in itself a finding about the gene and the disease.
melanoma (8 papers, 2020 to 2025). A malignant, usually aggressive tumor composed of atypical, neoplastic melanocytes. "In this respect, elevated expression of ATOX1 has been linked to increased tolerance to cisplatin in several types of cancer cell lines, including melanoma." (PMID 40721800, 2025). "In 2019, Kim and colleagues found that the copper chaperone ATOX1, highly expressed in melanoma cells, underlies the BRAFV600E signaling cascade." (PMID 36291728, 2022). "In this respect, ATOX1 is critical for the activation of the MEK-ERK signaling pathway in BRAFV600E-mutated melanomas, as the pharmacological inhibition of ATOX1 by DC_AC50 decreases the phosphorylation of ERK1/2 and reduces the growth of BRAF-mutated melanoma cells." (PMID 40721800, 2025). "For example, the siRNA-mediated knockdown of ATOX1 in wild-type BRAF melanoma cells significantly diminished the accumulation of copper ions and reduced the susceptibility of cells to combination therapy with trametinib and disulfiram." (PMID 40721800, 2025). "Suppression of cell proliferation in response to RNAi-mediated knockdown of ATOX1 was also found in non-small cell lung cancer, melanoma and colorectal cancer cells." (PMID 40721800, 2025). "Mechanistically, ATOX1 is crucial for copper uptake by melanoma cells exposed to the combination of trametinib and DSF/Cu, which subsequently induces JNK/JUN signaling and ER stress." (PMID 39970778, 2025). "This phenomenon can be, however, cancer type-specific as in melanoma cells, ATOX1 is predominantly localized in the cytosolic fraction." (PMID 40721800, 2025). "Another study found that ATOX1 is necessary for MAPK pathway activation in melanoma, which indirectly supports MEK1/2 copper binding." (PMID 39036924, 2024). "In parallel to the impaired copper accumulation, knockdown of ATOX1 significantly reduced the cytotoxic effect of trametinib plus CuET in the BRAF WT melanoma cell lines." (PMID 38263136, 2024). "Downregulation of ATOX1 via siRNA significantly diminished the accumulation of copper in both melanoma cell lines tested after treatment with the combination." (PMID 38263136, 2024). "In support of such a link, ATOX1 knockout in B-Raf proto-oncogene, serine/threonine kinase (BRAF) mutation-positive melanoma cells was found to reduce MAPK signaling." (PMID 31898157, 2020). "Accordingly, ATOX1 overexpression is correlated with poor survival in melanoma patients." (PMID 39970778, 2025). "Additionally, ATOX1 levels are significantly higher in cisplatin-resistant melanoma cells than in cisplatin-sensitive ovarian carcinoma cells." (PMID 40721800, 2025). "The role of ATOX1 as a nuclear copper shuttle has only recently been described but was previously unknown in melanoma cells." (PMID 38263136, 2024). "We therefore hypothesized that ATOX1 is involved in the combination-induced nuclear copper accumulation in BRAF WT melanoma cells." (PMID 38263136, 2024). "In melanoma, a correlation between the overexpression of Atox1 and poor prognosis was observed because the knockdown of Atox1 decreased cell growth and BRAF V600E-dependent signaling in human melanoma cell lines." (PMID 33271772, 2020).
Wilson disease (7 papers, 2012 to 2023). A very rare inherited multisystemic disease presenting non-specific neurological, hepatic, psychiatric or osseo-muscular manifestations due to excessive copper deposition in the body. "After cell uptake, Cu is transferred, via direct protein-protein interactions, from the chaperone Atox1 to the Wilson disease protein (WD) for incorporation into Cu-dependent enzymes." (PMID 26013029, 2015). "Here we use in vitro biophysical methods to deduce thermodynamic parameters of copper (Cu) transfer from the human copper chaperone Atox1 to the fourth metal-binding domain of the Wilson disease protein (WD4)." (PMID 22574136, 2012). "Based on affinity and NMR studies, Cu binding to a Wilson disease domain is favored over binding to Atox1 by a factor of 3–5." (PMID 22574136, 2012). "Here, for the first time, the energetic (enthalpic and entropic) contributions for the two elementary steps resulting in Cu transfer from the human chaperone Atox1 to the fourth metal-binding domain of the Wilson disease protein, WD4, have been dissected." (PMID 22574136, 2012). "Earlier in vitro and in silico work has shown that Cu transfer from Atox1 to metal-binding domains (WD) of the Wilson disease protein and metal-binding domains (MK) of the Menkes protein proceeds via a copper-bridged hetero-dimer complex where the metal is shared between the two metal-binding sites." (PMID 22574136, 2012). "The pathology generated by suppression of Atox1 or CCS gene in Drosophila neuronal tissues can serve as a powerful and reliable model system for Menkes and Wilson's diseases in human." (PMID 31575544, 2019). "In the human cytoplasm, after the uptake of Cu ions, the Cu chaperone Atox1 transports the metal to the membrane-bound ATP7A and ATP7B (Menke’s and Wilson disease proteins, respectively), two homologous P1B-type ATPases located in the trans-Golgi network." (PMID 27744583, 2017).
atherosclerosis (6 papers, 2022 to 2025). A disease characterized by the build-up of fatty material and calcium deposition in the arterial wall resulting in partial or complete occlusion of the arterial lumen. "In the case of atherosclerosis, the current study showed decreased atherosclerosis development on a high-fat diet in global Atox1-deficient mice, suggesting a proatherogenic role of Atox1." (PMID 36139494, 2022). "In conclusion, we demonstrated that Atox1-deficient mice showed decreased atherosclerosis development and identified downstream target genes regulated by nuclear Atox1 on the genome-wide scale in ECs." (PMID 36139494, 2022). "Functionally, Atox1-deficient mice showed decreased atherosclerosis development on a high-fat diet." (PMID 36139494, 2022). "It has been demonstrated that ATOX1 is involved in vascular smooth muscle cell migration in atherosclerosis and contributes to the neointimal formation." (PMID 41462995, 2025). "In summary, ATOX1 represents a promising therapeutic target for inflammation-related vascular diseases such as atherosclerosis." (PMID 38218941, 2024). "In studies of atherosclerosis, ATOX1 is increased in the intima of atherosclerotic lesions in ApoE−/− mice and localizes to the nucleus in pathologic conditions such as hypertensive and atherosclerotic vessels." (PMID 36774340, 2023). "Addressing the role of endothelial nuclear Atox1 in atherosclerosis by using EC-specific Atox1−/− mice, as well as EC-specific Atox1 overexpressing transgenic mice, is the subject of a future study." (PMID 36139494, 2022). "To investigate the functional significance of Atox1 in atherosclerosis in vivo, we used either Atox1−/− mice crossed with ApoE−/− mice (Atox1−/−/ApoE−/−) or ApoE−/− (control) mice on a 4-month Western diet." (PMID 36139494, 2022). "These discoveries unveil novel downstream targets of nuclear Atox1 that play a role in inflammation and reactive oxygen species (ROS) generation, offering valuable insights into the potential of targeting nuclear Atox1 for treating inflammatory conditions like atherosclerosis." (PMID 39519014, 2024). "Moreover, inhibitors of the copper chaperones ATOX1 and CCS, such as DC-AC50, show potential in treating atherosclerosis (AS)." (PMID 39519014, 2024).
lung carcinoma (6 papers, 2013 to 2025). "hsCRIP2 was proposed to bind Cu+ and interact with ATOX1 and has been implicated in modulating the autophagic response in the lung cancer cell line H1299." (PMID 39637238, 2024). "Cysteine-rich secretory protein 2 (CRIP2) has been identified as a nuclear interacting partner for ATOX1 in lung cancer cells." (PMID 40721800, 2025). "The results also showed the potential of Saccharomyces cerevisiae as a model organism in studying the capacity of ATOX1 as a therapeutic target for lung cancer therapy." (PMID 27401861, 2016). "ATOX1 also identified to play an important role in the copper-stimulated proliferation of non-small lung cancer cells and to be a potential therapeutic target for lung cancer therapy targeting copper metabolism." (PMID 27401861, 2016). "Both ATOX1 and ROCK1 were highly expressed and localized in the cytoplasm of Lewis lung cancer cells (LLCs), as confirmed by immunofluorescence." (PMID 40940984, 2025). "In Lewis lung cancer cells (LLCs), ATOX1 and ROCK1 up-regulate each other in a negative feedback manner." (PMID 40940984, 2025).
ovarian carcinoma (6 papers, 2013 to 2025). A malignant neoplasm originating from the surface ovarian epithelium. "The contribution of ATOX1 to the regulation of ovarian cancer cell sensitivity to cisplatin has been questioned by others using CRISPR-Cas9-mediated knockout of ATOX1." (PMID 40721800, 2025). "In addition to ATOX1, investigation of the potential of other copper transporters and chaperones in siRNA therapy of NSCLC and other cancers, such as ATP7B in ovarian cancer and ATP7A in neuroblastoma is warranted." (PMID 23624903, 2013).
colon cancer (4 papers, 2020 to 2025). "Another study showed that activin A-induced migration and colony formation of colon cancer cells were enhanced by nuclear translocation of ATOX1." (PMID 39036924, 2024). "The nuclear localization of Atox1 protein was assessed in two cell lines derived from the same colon cancer patient." (PMID 31961892, 2020). "Subcellular fractionation of colon cancer cell lines SW480 and SW620 cells was used to examine the cellular location of Atox1 in the face of activin A, a cytokine that stimulates colon cancer metastasis." (PMID 31961892, 2020). "Endogenous inhibition of Atox1 in metastatic SW620 human colon cancer cells decreased cellular migration, viability and colony formation, which was associated with decrease in cyclin D and p47 phox expression." (PMID 31961892, 2020). "The distinct nuclear localization of Atox1 protein in the colon cancer TMA prompted us to verify its subcellular distribution in CRC cell lines by cellular fractionation followed by immunoblotting." (PMID 31961892, 2020). "We observed immunoreactivity of Atox1 protein in both nuclear and cytoplasmic compartments of colon cancer TMA with very little Atox1 expression in normal tissue." (PMID 31961892, 2020). "Since cyclin D1 acts as a transcriptional regulator of cell proliferation and migration, and Atox1 is known to induce cyclin D1 transcription, we hypothesized that Atox1 could positively regulate colon cancer metastasis by influencing cyclin D1 expression." (PMID 31961892, 2020). "To understand the molecular mechanisms of metastasis in colon cancer, we investigated whether the copper chaperone antioxidant-1 (Atox1) protein plays a role in this process." (PMID 31961892, 2020). "Activin A treatment promotes Atox1 nuclear translocation in both colon cancer cell lines." (PMID 31961892, 2020). "Interestingly, we observed Atox1 cytoplasmic sequestration in SW480 colon cancer cell line and this restraint was released upon activin A stimulation that induced cytoplasmic to nuclear transport." (PMID 31961892, 2020). "Stimulation of colon cancer metastasis with activin A promotes ATOX1 nuclear translocation in metastatic SW620 and nonmetastatic SW480 colon cancer cell lines." (PMID 34504870, 2021). "Consistent with this, Atox1 is highly expressed in the nucleus in metastatic SW620 colon cancer cell line, while Atox1 is expressed more in the cytosol in non-metastatic SW480 colon cancer cell lines." (PMID 31961892, 2020). "Using CRC cell lines developed from non-metastatic colon cancer tumor and from a lymph node metastasis from the same patient, we investigated the potential role of nuclear Atox1 in CRC and its regulation by activin A, a cytokine known to play a role in metastatic CRC." (PMID 31961892, 2020). "Additionally, overexpression of nuclear-targeted but not copper binding domain-mutated Atox1 in SW480 cells increased colony formation and cell migration that was further augmented by activin A stimulation, a known enhancer of colon cancer metastasis." (PMID 31961892, 2020). "Although the presence of Atox1 in the nucleus has been reported in different cancers, this is the first demonstration that activin A stimulates cytoplasmic to nuclear transport of Atox1 leading to increased cellular migration and colony formation in non-metastatic colon cancer cell line." (PMID 31961892, 2020). "Importantly, we found that nuclear-targeted Atox1 induces migration and colony formation in non-metastatic SW480 colon cancer cells that was further increased upon activin A stimulation." (PMID 31961892, 2020).
colorectal cancer (4 papers, 2020 to 2025). A primary or metastatic malignant neoplasm that affects the colon or rectum. "Taken together, understanding the combined actions of activin A and Atox1 may improve the current staging of colorectal cancer patients." (PMID 31961892, 2020). "The nuclear function of ATOX1 has also been investigated in a study comparing colorectal cancer cells with metastatic potential (SW620) and nonmetastatic cells (SW480), and increased accumulation of ATOX1 protein in the nuclear fractions of SW620 cells has been reported." (PMID 40721800, 2025).
endometritis (4 papers, 2023 to 2025). An acute or chronic, usually bacterial infectious process affecting the endometrium. "The IL10, ATOX1, and GST genes were expressed at significantly lower amounts in endometritis-affected cows according to the molecular changes." (PMID 37368756, 2023). "The IL10, ATOX1, and GST genes were expressed at substantially lower levels in endometritis-affected cows." (PMID 37368756, 2023). "Nucleotide sequence variations between healthy and endometritis-affected cows were revealed using PCR-DNA sequencing for immune (TLR4, TLR7, TNF-α, IL10, NCF4, and LITAF), antioxidant (ATOX1, GST, and OXSR1), and erythritol-related (TKT, RPIA, and AMPD1) genes were reported by44." (PMID 38459095, 2024). "The levels of the PRLR, LTF, CLA-DRB3.2, beta defensin, TLR2, TLR4, and CCL5 genes were significantly up-regulated in postparturient goats with endometritis compared to tolerant ones, while the GPX4, GST, SOD3, CAT, and ATOX1 gene patterns demonstrated the opposite tendency." (PMID 39195794, 2024). "Nucleotide sequence variations between healthy and endometritis-affected cows were revealed using PCR-DNA sequencing for immune (TLR4, TLR7, TNF-α, IL10, NCF4, and LITAF), antioxidant (ATOX1, GST, and OXSR1), and erythritol-related (TKT, RPIA, and AMPD1) genes." (PMID 37368756, 2023). "Molecular genetic analyses of the immunological (TLR4, TLR7, TNF-α, IL10, NCF4, and LITAF), antioxidant (ATOX1, GST, and OXSR1), and erythritol-related (TKT, RPIA, and AMPD1) genes comparing healthy and endometritis cows found differences in nucleotide sequence and transcript levels." (PMID 37368756, 2023). "Single nucleotide variants (SNPs) in the genes were discovered using PCR-DNA sequencing for immune (TLR4, TLR7, TNF-α, IL10, NCF4, and LITAF), antioxidant (ATOX1, GST, and OXSR1), and erythritol-related (TKT, RPIA, and AMPD1) genes found in resistant and endometritis-infected Holstein dairy cows." (PMID 37368756, 2023). "The immune (TLR4, TLR7, TNF-α, IL10, NCF4, and LITAF), antioxidant (ATOX1, GST, and OXSR1), and erythritol-related (TKT, RPIA, and AMPD1) genes in endometritis-affected and healthy Holstein dairy cows were characterized in this research using a PCR-DNA sequencing technique." (PMID 37368756, 2023).
ischemia (4 papers, 2015 to 2016). A hypoperfusion of the BLOOD through an organ or tissue caused by a PATHOLOGIC CONSTRICTION or obstruction of its BLOOD VESSELS, or an absence of BLOOD CIRCULATION. "We next examined a role of Atox1 in arteriogenesis and angiogenesis, which contributes to ischemia-induced neovascularization." (PMID 26437801, 2015). "Ischemia hindlimb model with micro-CT analysis and sponge implant assay reveal that Atox1 is involved in ischemia/inflammation-induced angiogenesis and arteriogenesis." (PMID 26437801, 2015). "In the Tat-Atox1 protein treated ischaemia group, few GFAP-immunoreactive astrocytes featuring abnormal thorn-shaped bodies and cytoplasm were found while the remaining astrocytes had a thread-like morphology with thorn-shaped bodies and a small amount of cytoplasm." (PMID 25781353, 2015). "Similarly, in the animal ischemia model, transduction of Atox1 decreased activation of astrocytes and microglia as well as lipid peroxidation in the hippocampus after ischemic insult, indicating that transduced Atox1 protects against oxidative stress-induced neuronal damage in ischemia." (PMID 27472369, 2016).
diabetes (3 papers, 2014 to 2023). "ATOX1 can protect pancreatic β-cells and induce diabetes mellitus." (PMID 37293508, 2023). "This suggests that persistent Atox1 localization in the nucleus may mimic pathological conditions, such as diabetes, in which reparative angiogenesis is impaired." (PMID 36139494, 2022). "Furthermore, diabetes depressed levels of additional intracellular copper-transporting proteins, including antioxidant-protein-1 (ATOX1) and copper-transporting-ATPase-2 (ATP7B), whereas TETA elevated copper-transporting-ATPase-1 (ATP7A)." (PMID 24927960, 2014).
Breast Tumor (2 papers, 2020 to 2021). "We performed ATOX1 immunohistochemical staining of breast tumor material (before TM treatment) of 47 patients enrolled in the phase II TM clinical trial and evaluated ATOX1 expression levels in relation with patient outcome after TM treatment." (PMID 34944703, 2021).
diffuse large B-cell lymphoma (2 papers, 2024 to 2025). "A central regulatory function of ATOX1 in modulating cell cycle progression has been comprehensively reported in a recent study on diffuse large B-cell lymphoma (DLBCL) cell lines and primary DLBCL samples." (PMID 40721800, 2025).
Hypertension (2 papers, 2016 to 2024). The presence of chronic increased pressure in the systemic arterial system. "It was further demonstrated that angiotensin II-dependent upregulation of SOD3 requires Atox1 and that genetic ablation of Atox1 exacerbated hypertension and associated ROS production." (PMID 27472369, 2016). "For instance, in angiotensin II (Ang II)-induced hypertension, the antioxidant 1 copper chaperone (Atox1) raises blood pressure by reducing extracellular oxygen anions and increasing the expression and activity of vascular superoxide dismutase 3 (SOD3)." (PMID 39267854, 2024). "Therefore, Atox1 and ATP7A likely play significant roles in hypertension by regulating both kidney and brain functions." (PMID 39267854, 2024).
ischemic disease (2 papers, 2015 to 2023). Lack of blood supply to an area of the body, resulting in impairment of tissue oxygenation. "Previous findings suggest a link between the copper transport protein ATOX1 and NADPH oxidase in inflammatory neovascularization, indicating that ATOX1 is a potential therapeutic target for the treatment of ischemic disease." (PMID 36718454, 2023).